MTOR (mechanistic target of rapamycin kinase)
Diseases named in the same sentence as MTOR in open-access papers (continued):
Sharing a sentence is not in itself a finding about the gene and the disease.
ependymoma (4 papers, 2021 to 2025). A WHO grade II, slow growing tumor of children and young adults, usually located intraventricularly. "Furthermore, additional immunohistochemistry studies of pediatric ependymomas tissue revealed that 20 out of 23 (87%) pediatric ependymomas were immunoreactive for phosphorylated S6, a biomarker that has been shown to be associated with response to mTOR pathway-targeted therapy." (PMID 36950217, 2023). "The rationale supporting this clinical trial was based upon both preclinical and clinical evidence for activation of the mTOR signaling cascade in pediatric ependymomas." (PMID 36950217, 2023). "Pre-clinical studies on mouse ependymoma cell-lines reported that inhibition of the mTOR-pathway can induce autophagy in EPN and showed an increased survival in mice transplanted with such cell-lines when treated with sirolimus." (PMID 34657224, 2021). "A phase II clinical trial (ClinicalTrials.gov identifier: NCT02155920) of single-agent everolimus was performed to test the hypothesis that mTOR pathway inhibition would result in tumor responses for children with recurrent and/or progressive ependymomas." (PMID 36950217, 2023). "The study is unable to comment upon whether mTOR pathway-targeted therapy has activity against PF-B ependymoma or newly diagnosed tumors." (PMID 36950217, 2023). "Preclinical studies have suggested that mTOR pathway signaling may be a potential therapeutic target for childhood ependymoma." (PMID 36950217, 2023). "From these reports, it would be reasonable to test the hypothesis of whether a related mTOR pathway inhibitor, everolimus, might have activity against ependymoma." (PMID 36950217, 2023). "It remains unknown whether mTOR pathway-targeted therapy may have a role against other subtypes of ependymoma, such as PF-B, supratentorial ependymomas or spinal cord ependymomas." (PMID 36950217, 2023). "The hypothesis of this study was that children with recurrent and/or progressive ependymomas would respond to mTOR pathway inhibition and experience minimal toxicity." (PMID 36950217, 2023). "Nonetheless, the role of protein kinase signaling has been implied in ependymoma tumorigenesis, prompting several ongoing studies evaluating TKIs targeting RET, ALK, ROS, IGFR, PDGFR, FGFR, or EGFR, as well as inhibitors targeting PI3K, mTOR, KIT, and CDK4." (PMID 40238025, 2025). "This study indicates that everolimus, an inhibitor of the mTOR pathway, does not have anti-tumor activity for children with recurrent PF-A ependymoma." (PMID 36950217, 2023). "Limitations of this study are several and include the following: There is poor understanding of the inconsistency between the identified preclinical mTOR pathway activation and the absence of anti-tumor activity of everolimus against pediatric ependymoma." (PMID 36950217, 2023). "In conclusion, although the majority of tumors from subjects in this study had immunohistochemical evidence suggesting mTOR pathway activation, this study suggests that single-agent everolimus has no meaningful activity against pediatric PF-A ependymoma." (PMID 36950217, 2023). "The authors found that high expression of TPR was associated with increased HSF1 and HSPA/HSP70 expression in ependymoma patients and showed that MTOR inhibition by rapamycin therapeutically suppressed TPR expression and reduced tumor size in an ependymoma mouse xenograft model." (PMID 36197606, 2022).
epithelioid sarcoma (4 papers, 2014 to 2024). An aggressive malignant neoplasm of uncertain differentiation, characterized by the presence of epithelioid cells forming nodular patterns. "Furthermore, when inhibited, the mTOR pathway, a potential target in epithelioid sarcoma treatment, can trigger AKT reactivation, reducing mTOR inhibitors’ effectiveness." (PMID 39329778, 2024). "In epithelioid sarcoma, EGFR overexpression is characteristic and combined inhibition of EGFR and mTOR has been suggested." (PMID 34281526, 2021).
folate deficiency (4 papers, 2017 to 2025). A nutritional condition produced by a deficiency of FOLIC ACID in the diet. "Through folate sensing by mTOR, maternal folate deficiency has been shown to result in reduced placental amino acid transport and restricted fetal growth." (PMID 40414302, 2025). "It is possible that the effect of maternal folate deficiency on placental function is mediated by indirect effects rather by placental mTOR folate sensing." (PMID 28638048, 2017). "Fetal weight was reduced in trophoblast-specific inducible Mtor knockout mice, which is similar in magnitude to that observed in other mouse models either with inhibition of placental mTOR signaling due to maternal folate deficiency, or following administration of rapamycin to pregnant mice." (PMID 40534504, 2025).
Gaucher disease (4 papers, 2019 to 2025). Gaucher disease (GD) is a lysosomal storage disorder encompassing three main forms (types 1, 2 and 3), a fetal form and a variant with cardiac involvement (Gaucher disease - ophthalmoplegia - cardiovascular calcification or Gaucher-like disease). "We also discuss how rare disorders such as Gaucher disease and ultra-rare genetic syndromes can provide insights into cancer and mTOR-driven metabolism, respectively." (PMID 40210765, 2025).
germ cell tumor (4 papers, 2015 to 2023). A benign or malignant, gonadal or extragonadal neoplasm that originates from germ cells. "TC usually starts as GCNIS and later, alterations in pathways regulating cell fate and proliferation (such as PI3K/Akt/mTOR signaling axis), result in the generation of invasive germ cell tumors." (PMID 36969070, 2023). "A previous study reported activation of the mTOR pathway in 94.4% of patients with intracranial germ cell tumors." (PMID 36969070, 2023).
granulosa cell tumor (4 papers, 2013 to 2019). A slow-growing, malignant tumor, characterize by the presence of granulosa-like cells and Call-Exner bodies, that is almost always found in the ovary. "Emerging data from animal studies suggest that Forkhead box O3 (FOXO3), phosphatase and tensin homolog (PTEN) and mammalian target of rapamycin (mTOR) pathways converge on the same follicle dormancy and granulosa cell tumor formation phenotypes." (PMID 29549247, 2018). "A synergistic growth inhibition was found by coupling DAS or mTOR inhibitors with PAC in ovarian granulosa cell tumor cells." (PMID 29765318, 2018). "Although the role of mTOR and p-mTOR in the proliferation of granulosa cell and in vitro SIGC line is well-established, no rigorously validated immunohistochemical study or targeted therapy on human granulosa cell tumors has been reported to date." (PMID 30592193, 2019).
hyperphosphatemia (4 papers, 2018 to 2022). Abnormally high level of phosphate in the blood. "To explore the intracellular mechanisms involved in senescence induced by hyperphosphatemia, we analysed the activation of mTOR and the autophagic flux in the presence of 10 mM BGP." (PMID 30271655, 2018). "The changes in p62 and in the LC3II/LC3I ratio were inhibited with rapamycin, indicating that the reduction in autophagy was dependent on the activation of mTOR by hyperphosphatemia." (PMID 30271655, 2018). "Hyperphosphatemia, another condition prevalent in CKD due to the high concentration of inorganic phosphate, suppresses the mammalian target of rapamycin (mTOR) signaling." (PMID 33917965, 2021). "We demonstrate that the hyperphosphatemia is not able to induce senescence in the presence of rapamycin, indicating that the activation of mTOR and the reduction in autophagy are essential in the effect of high phosphate on senescence." (PMID 30271655, 2018).
intestinal polyp (4 papers, 2011 to 2023). Discrete abnormal tissue masses that protrude into the lumen of the intestine. "In this study, we show that mTOR inhibition potently suppresses intestinal polyp formation, regresses established polyps, and prolongs lifespan of APCMin/+ mice." (PMID 37138032, 2023). "Dysregulated Wnt/β-catenin signaling has been shown to induce mTOR expression and signaling in intestinal polyps of mutant APC mice, and we have shown that mTOR expression is elevated in uteri of Amhr2-Cre;Ctnnb1Δ(ex3)/+ mice." (PMID 21695255, 2011). "Together, these findings suggest mTOR and elevated Myc as a vulnerability in mutant APC-driven intestinal polyps, and a potential role of cell death in the activation of local immune environment." (PMID 37138032, 2023). "For example, intestinal polyps in human PJS patients and an Lkb1 heterozygous mouse model show upregulation of the mTOR activity and expansion of smooth muscle compartment." (PMID 22916036, 2012).
Large vessel vasculitis (4 papers, 2021 to 2023). A type of vasculitis (inflammation of blood vessel walls) affecting large arteries such as the aorta and branches of the aorta. "Another study that analyzed the involvement of mammalian target of rapamycin (mTOR) in large-vessel vasculitis suggested that humoral immunity plays an important role in Takayasu arteritis but not GCA." (PMID 35629030, 2022). "Furthermore, the fact that HuMoSCs inhibit the mTOR complex is therapeutically relevant since previous data have shown that the mTORC1 pathway plays a central role in driving T-cell inflammation and vascular injury in large vessel vasculitis." (PMID 36895571, 2023).
leukoplakia (4 papers, 2013 to 2025). A white patch or plaque on a mucous membrane that cannot be characterized clinically or pathologically as any other disease. "Immunohistochemistry for p-Akt, p-mTOR, and phospho-pS6 was performed in 40 OLP, 20 oral leukoplakias (OL), 10 OSCC, and 10 control samples of NM." (PMID 24228033, 2013). "Unlike in OSCC, the average levels of iPANDA values for AKT/mTOR and other survival and mitogenic pathways, such as ERK, JNK, RAS/MAPK, p38, PAK, integrin/ILK and TGFβ signaling, were substantially lower in most leukoplakia samples when compared to the normal cohort." (PMID 28580171, 2017).
lipodystrophy (4 papers, 2020 to 2026). A congenital or acquired disorder characterized by abnormal loss or redistribution of the adipose tissue in the body. "The second important question addressed by this study was whether inhibition of mTOR with rapamycin is likely to be safe in MFN2 R707W-related lipodystrophy." (PMID 40759924, 2025). "Furthermore, footprint analysis of bulk transcriptomic data from adipose tissue of humans withMFN2R707W-related lipodystrophy andMfn2R707W/R707Wmice suggested that mTOR signalling was upregulated." (PMID 40759924, 2025).
lipoma (4 papers, 2018 to 2026). A benign, usually painless, well-circumscribed lipomatous tumor composed of adipose tissue. "We observed a loss of heterozygosity in the lipoma tissue, resulting in TSC1 deficiency and subsequent activation of the mechanistic target of rapamycin (mTOR) signaling pathway." (PMID 42286631, 2026).
lymphoid neoplasm (4 papers, 2018 to 2023). A neoplasm composed of a lymphocytic cell population which is usually malignant (clonal) by molecular genetic and/or immunophenotypic analysis. "Our results suggest that drugs blocking translation, IL-15, JAK or mTOR downstream of this cytokine might concur in the treatment of lymphoid tumors of NK cell origin depending on MYC." (PMID 37105715, 2023). "Based on these clinical results, the clinical development of all but three dual PI3K/mTOR inhibitors has been stopped, although they could be beneficial for some patients that were affected by lymphoid neoplasms." (PMID 32033478, 2020).
lymphopenia (4 papers, 2021 to 2025). Reduction in the number of lymphocytes. "As an example, some evidence suggests that lymphopenia is a risk factor for COVID-19 infection – the former being the mode of action of mammalian target of rapamycin [mTOR] inhibitors." (PMID 33491531, 2021). "The consequent hyperactivation of the PI3K-Akt-mTOR pathway leads to an impaired T- and B-cells differentiation and function, causing progressive lymphopenia, hypogammaglobulinemia and hyper IgM." (PMID 34540765, 2021). "It was believed that lymphopenia is a risk factor for SARS-CoV-2, which is the mechanism of action of mammalian target of rapamycin (mTOR) inhibitors." (PMID 38313994, 2024).
lymphoproliferative disorder (4 papers, 2014 to 2022). "Mammalian target of rapamycin (mTOR) inhibitors have been shown to reduce proliferation of lymphoid cells; thus, their use for immunosuppression after heart transplantation (HT) may reduce post-transplant lymphoproliferative disorder (PTLD) risk." (PMID 35054016, 2022).
macrosomia (4 papers, 2020 to 2025). "Given the association between mTOR signaling and fetal overgrowth, further research is needed to determine whether modifying treatment strategies could mitigate macrosomia risk in insulin-treated GDM pregnancies." (PMID 40136665, 2025). "In placental tissue, excessive mTOR activation may contribute to trophoblast hyperplasia, increasing placental size and nutrient transfer to the fetus, thereby predisposing the offspring to macrosomia." (PMID 40136665, 2025). "It is believed that IGF-1 stimulates macrosomia via mammalian target of rapamycin (mTOR) activation and the subsequent increase in essential and non-essential amino acid transporters in the placenta of women with GDM." (PMID 38812661, 2024). "Studies suggested that the placental mTOR is upregulated in pregnancies complicated by GDM, and mTOR overactivation is linked to fetal macrosomia." (PMID 33240030, 2020).
Merkel Cell Carcinoma (4 papers, 2014 to 2024). "Importantly, aberrations in the PI3K/AKT/mTOR pathway (AKT2, FBXW7, NF1, PIK3CA, PIK3R1, PTEN or RICTOR) were also commonly seen in Merkel cell carcinomas (9/17 [53%])." (PMID 26981779, 2016).
metastatic colorectal cancer (4 papers, 2014 to 2021). "In the EGFR-related signaling pathway, PI3K/Akt, MAPK, and mTor were involved in metastatic colorectal cancer." (PMID 34067437, 2021). "In this study, we analyzed the functional role of the PI3K/AKT/mTOR signaling pathway in the CTC-MCC-41 line, derived from a patient with metastatic colorectal cancer." (PMID 32962206, 2020).
metastatic prostate carcinoma (4 papers, 2016 to 2023). A carcinoma that arises from the prostate gland and has spread to other anatomic sites. "In metastatic prostate cancer, piperine regulated the Akt/mTOR/MMP-9 signaling pathway and reduced metastasis." (PMID 36678600, 2023).
mycobacterial infection (4 papers, 2022 to 2024). "Knockdown of miR-126 increases susceptibility to mycobacterial infection which can be independently reversed by targeting Tsc1/mTOR or ccr2 implicating macrophage function." (PMID 38307625, 2024). "As mTOR activation increases during mycobacterial infection, we sought to determine if mTOR activation led to autophagy inhibition by pathogenic mycobacteria in a dose-dependent manner." (PMID 36104771, 2022). "We link infection-induced miR-126 to Tsc1 via activation of the mTOR pathway and improved macrophage function because of regulation of a Cxcl12/Ccl2/Ccr2 signalling axis during the early stages of mycobacterial infection." (PMID 38307625, 2024). "Inhibiting mTOR with rapamycin reduces autophagy, which, in turn, favors bacterial replication like the data shown during mycobacterium infection." (PMID 38399700, 2024). "NCoR1 KD mo-MΦ showed lower AMPK activity at 2 h and 24 h post Mycobacterium infection, which is consistent with the mTOR activity." (PMID 37590294, 2023). "To identify the role of AMPK/mTOR signalling culminating into dysregulated autophagy in NCoR1 KD mo-MΦ upon mycobacterial infection, we treated the cells with metformin, an AMPK activator." (PMID 37590294, 2023). "Surprisingly, we observed that all three mycobacterial infections enhanced mTOR activation and autophagy induction simultaneously in a dose-dependent manner, which hints at dysregulation in mTOR-dependent autophagy for all three mycobacteria species." (PMID 36104771, 2022). "Thus, we concluded that autophagy dysregulation indicates that mycobacterial infection-induced autophagy is independent of mTOR, regardless of species." (PMID 36104771, 2022).
myeloproliferative neoplasm (4 papers, 2013 to 2022). A clonal hematopoietic stem cell disorder, characterized by proliferation in the bone marrow of one or more of the myeloid (i.e., granulocytic, erythroid, megakaryocytic, and mast cell) lineages. "The AKT/mTOR signaling pathway and its downstream effector p70 S6 kinase are increased in myeloproliferative neoplasm (MPN) patients, with JAK2V617F mutation dependance." (PMID 35204748, 2022). "At this regard, combination of rapamycin with ABT-737, an inhibitor of Bcl-XL, has recently been shown to provoke synergistic effects in mice with a myeloproliferative disorder due to constitutively active STAT5 and persistent activation of Akt/mTOR signalling." (PMID 23382981, 2013).
Optic neuropathy (4 papers, 2017 to 2026). "Thus, inactivating PTEN activates Akt and mTOR, facilitates the RGCs survival after optic neuropathy." (PMID 28323869, 2017). "No change in mTOR suggests that the advantage conferred to OHT patients resistant to optic neuropathy did not include a drive toward making more mitochondria." (PMID 28424571, 2017). "One regulatory complex important for mitochondrial biogenesis, mTOR, was no different in tissues between patients with ocular hypertension (OHT) and those with glaucoma even though the OHT patients demonstrated increased mitochondrial efficiency and no optic neuropathy." (PMID 28424571, 2017).
oral mucositis (4 papers, 2016 to 2023). Inflammation of the mucous membranes of any of the structures in the mouth. "Among them, the mammalian target of rapamycin (mTOR)-inhibitor promotes a severe mucosal toxicity that differs from conventional oral mucositis." (PMID 33028357, 2020).
Osteopenia (4 papers, 2015 to 2022). Osteopenia is a term to define bone density that is not normal but also not as low as osteoporosis. "Deriving from exosomes of mesenchymal stem cells, miR-151-5p determined osteogenic versus adipogenic fate and rescued the osteopenia phenotype in Tsk/+ mice by inhibiting the IL-4Rα/mTOR pathway." (PMID 35464474, 2022). "Accordingly, to counteract the MSC dysfunction and osteopenia induced by mechanical unloading, rapamycin inhibition of mTOR signaling functions as a downstream therapeutic to protect against TNFα deficiency." (PMID 33384406, 2021). "Prevented osteopenia, skin tighten and immune disorders by inhibiting the IL-4Rα/mTOR pathway." (PMID 35464474, 2022). "Accordingly, genetic or pharmacological inhibition of M-CSF or mTOR signaling, but not IL-17 signaling, attenuates osteoclastogenesis and osteopenia in scurfy." (PMID 25880090, 2015).
ovarian adenocarcinoma (4 papers, 2019 to 2025). An adenocarcinoma that arises from the ovary. "Treatment with CUR alone significantly inhibited the growth of human ovarian adenocarcinoma SKOV-3/CDDP CDDP-resistant subline cells by inhibition the gene expression of the antioxidant enzymes (SOD1, SOD2, GPX1, CAT, and HO1), transcription factor NFE2L2 and signaling pathway (PIK3CA/AKT1/MTOR)." (PMID 39859517, 2025).
Ovarian cyst (4 papers, 2012 to 2021). The presence of one or more cysts of the ovary. "Recently, chronic treatment with mTOR inhibitors has been reported to increase the risk of menstrual-cycle disturbances and ovarian cysts in women and to lead to reduced ovulation in mice." (PMID 23326514, 2013). "Disturbed hormone levels and ovarian cysts associated with mTOR inhibitor therapy have also been described, although the concrete mechanism was unknown." (PMID 34217357, 2021).